IL6 (interleukin 6)
Diseases named in the same sentence as IL6 in open-access papers (continued):
Sharing a sentence is not in itself a finding about the gene and the disease.
injury (continued). "Blast limb trauma triggered the local and system inflammatory response, characterized by release of cytokines, such as TNF-α and IL-6, and those cytokines play important roles in the early phase of acute lung injury." (PMID 23527096, 2013). "For example, resolvin E1 can decrease the levels of IL-6 and IL-1β found in lung tissue following HCl-induced acute lung injury." (PMID 23663457, 2013). "Patients with persistent sciaticpain display elevated IL-6 levels in the blood and following traumatic brain injury, increased IL-6 levels are foundin the brain." (PMID 17641729, 2007). "In a rat acute lung injury model, taurine could reduce the content of pro-inflammatory cytokines IL-1β and interleukin-6 (IL-6), alleviate pulmonary inflammatory response, and demonstrate therapeutic potential for acute lung injury." (PMID 41380328, 2025). "Similarly, Sauer, Peukert have reported that MXF reduced levels of TNF-α and IL-6 in a mouse model of acute lung injury." (PMID 40327662, 2025). "Su’s study demonstrated that Yinchen and a Gancao Decoction significantly reduced the expression levels of IL-1β, IL-6, and TNF-α in the hepatocyte and revealed that hepatocyte necrosis caused by cholestatic liver injury can be alleviated by reducing the release of inflammatory cytokines." (PMID 41471340, 2025). "Furthermore, the concentration of CSF IL-6 was correlated with nerve injury extent, which gated the occurrence of widespread pain." (PMID 38419042, 2024). "Trauma patients had significantly upregulated proteins associated with immune activation (IL-23, MIP-5), immunosuppression (IL-10) and pleiotropic cytokines (IL-29, IL-6)." (PMID 38903094, 2024). "We designed an effective chemically modified anti-TIMP1 siRNA and showed that Timp1 silencing correlates with a decrease in the pro-inflammatory cytokine IL6 secretion in cultured macrophage cells and reduces the severity of LPS-induced acute lung injury in a mouse model." (PMID 36675165, 2023). "More anxious patients may exhibit higher levels of proinflammatory cytokines interleukin-6 (IL-6), which might interfere with recovery from the nerve injury in CIPN, resulting in more CIPN over time." (PMID 35543818, 2022). "Moreover, TA was found to inhibit inflammatory response and apoptosis through attenuation of TNF-α, IL-1β, IL-6, Bax, Bcl-2, and caspase-3 in CCl4-induced liver injury in mice." (PMID 36358896, 2022). "It has been suggested that IL‐6 might be released as a protective response after HI brain injury and is involved in the repair process in the sub‐acute stage of HIE." (PMID 37786746, 2022). "Dexmedetomidine-mediated effects on CAP have been demonstrated to alleviate renal ischaemia–reperfusion injury and LPS-induced acute lung injury in rodent models, decreasing inflammatory mediators (amongst others interleukin [IL]-1β, IL-6, and tumour necrosis factor-alpha [TNF-α])." (PMID 37588789, 2022). "Inflammatory mediators are thought to cause severe inflammatory responses to tissue damage, and IL-6, IP-10 and MCP-1 have been found to be associated with acute lung injury and even poor prognosis and higher risk of death in SARS-CoV-1 and SARS-CoV-2 infections." (PMID 35656028, 2022). "A recent study has shown that activated PARP-1 upregulates the expression level of IL-6 in LPS-induced acute lung injury, which promotes the differentiation of T helper 17 (Th17) cells and represses the differentiation of CD4+CD25+Foxp3+ regulatory T (Treg) cells." (PMID 35190759, 2022). "In addition, in traumatic brain injury, IL-6 was a well-established biomarker for confirming the presence and severity of brain lesions as well as predicting the probable neurological outcome." (PMID 35654991, 2022).
injury (continued). "Blocking the effect of rubral IL-6 relieves pathological pain induced by nerve injury, while intrarubral administration of exogenous IL-6 can dose-dependently evoke obvious tactile allodynia in naive rats, indicating that IL-6 yields a facilitatory effect in the maintenance of neuropathic pain." (PMID 35465093, 2022). "The CSF: serum ratio of IL-6 levels was sufficiently consistent to act as a potential biomarker of intracranial aneurysms, while increased levels of IL-6 in rat brain parenchyma occurred in parallel with plasma and CSF values and with the severity of traumatic brain injury." (PMID 36507331, 2022). "Moreover, elevated levels of IL-6 lead to acute lung injury and suppress the functions of T lymphocytes, macrophages and dendritic cells, which impair the immune system." (PMID 35237162, 2022). "Studies have shown that the CM of bone marrow mesenchymal stem cells (BMSCs) reduced the serum concentrations of TNF-α, IL-1β and IL-6; in contrast, the level of the anti-inflammatory cytokine IL-10 significantly increased in rats with radiation-induced liver injury." (PMID 33781342, 2021). "Moreover, the increase of IL-6 in the serum of mice in the low-dose group is related to the activation of inflammatory factors after alcohol-induced liver injury." (PMID 34633988, 2021). "A previous study reported that baicalin could diminish levels of pro-inflammatory mediators, TNF-α, IL-6 and IL-1β, in acute lung injury, functioning as a potential therapeutic candidate, which was largely consistent with the observations of our study." (PMID 34053448, 2021). "For example, the TLR4 rs10116253-2242C allele enhances the transcriptional activities and expression of TLR4, and trauma patients with the variant C allele have a greater capacity to produce the pro-inflammatory cytokines TNF-α and IL-6 than those with other alleles." (PMID 30683156, 2019). "In head-injured children, serum IL-6 and CRP levels are elevated and correlated to the severity of head trauma and increased levels of IL-6 in the early phase of severe acute traumatic brain injury is associated with the high inflammatory response such as development of ARDS." (PMID 31805967, 2019). "During brain injury, IL-6 signaling may not only induce the chemotactic migration of inflammatory cells to the site of lesion but may also promote T-cell polarization." (PMID 31667013, 2019). "The inhibition of TNF-α, IL-1β, and IL-6 production by AVA might occur through pathways that converge on NF-κB activation because they can regulate cytokine production in LPS-induced acute lung injury." (PMID 29483931, 2018). "The results showed that taraxasterol could inhibit inflammatory cytokines TNF-α and IL-6 production in mice with ethanol-induced liver injury." (PMID 30344887, 2018). "Elevated concentrations of proinflammatory cytokines, such as interleukin-1β (IL-1β), interleukin-6 (IL-6) and tumor necrosis factor-α (TNFα), are frequently detected in the brain, cord blood, and amniotic fluid of very preterm infants with brain injury." (PMID 25898410, 2015). "In addition, the proinflammatory cytokine IL-6 has been demonstrated to be important in the pathogenesis of OJ-induced liver injury." (PMID 24944590, 2014). "We also found that OMT could suppress the synthesis of tumor necrosis factor –alpha (TNF-α), interleukin-1beta (IL-1β) and interleukin-6 (IL-6) after traumatic brain injury via NF-κB pathway." (PMID 24250585, 2013). "One explanation might be an alteration in the inflammatory response as suggested by a recent study that reported that obese patients with acute lung injury have lower levels of several proinflammatory cytokines including surfactant proteins, IL-6 and IL-8." (PMID 24533210, 2012). "IL-6 has been shown to contribute to cardiovascular dysfunction induced by acute lung injury." (PMID 23072542, 2012).
injury (continued). "We investigated further whether these Gr-1+CD11b+ cells induced by IL-6 were sufficient and essential to protect 2A-induced liver injury in vivo." (PMID 21394214, 2011). "For instance, IL-6 serum concentrations can reach as high as 1100 pg/mL (normal: ≤1.8 pg/mL), whereas IL-8 levels may range from 0 to 2400 pg/mL (normal: ≤14.6 pg/mL) following severe head trauma." (PMID 41226738, 2025). "In addition, previous data suggests that IL-6 trans-signaling may play an essential role in AP-related acute lung injury in mouse models." (PMID 38529201, 2024). "Therefore, we investigated whether ICD affects IL-6 production in LPS activated macrophages and acute lung injury mouse model." (PMID 36902060, 2023). "Specifically, given that COVID-19 infection has been associated with liver enzyme abnormalities, elevated plasma levels of IL-6, and increased risks for kidney injury and renal failure, LpX and/or LpZ particles may constitute key prognostic biomarkers in such patients." (PMID 34572275, 2021). "In addition, IL-1β, IL-6, TNFα, and the chemokines CCL5 and CXCL2 (which were all upregulated by LPA in primary microglia) are implicated as modulators of the neuroinflammatory response during traumatic brain injury where LPA levels are increased." (PMID 27565558, 2016). "■Decreased COX-2 and CXCL-8 gene expression in human bronchial epithelial cells;■Reduced IL-6 and TNF-α pulmonary levels in a rat model of LPS-induced acute lung injury." (PMID 40298549, 2025). "This is supported by previous findings showing that S100A8 triggers IL-6 and MCP-1 production and neutrophil recruitment through TLR4 activation in alveolar epithelial cells, exacerbating inflammation in models of acute lung injury." (PMID 40723384, 2025). "D-gal induction led to upregulated mRNA expression of pro-inflammatory cytokines (IL-6, IL-1β, and TNF-α), which are core drivers of the inflammatory cascade in persistent liver injury." (PMID 41614837, 2025). "Among the earliest molecular mediators released after cerebral trauma are the pro-inflammatory cytokines tumor necrosis factor-α (TNF-α) and interleukin-6 (IL-6)." (PMID 41463131, 2025). "Silencing of MNK2 leads to diminished histopathological alterations in the lungs, evidenced by lower neutrophil levels and reduced IL-6 and TNF-α production in cases of acute lung injury." (PMID 39884255, 2025). "The administration of JYGBF significantly ameliorated acute lung injury (ALI) and inhibited overactivated inflammatory response (MIP-2, IL-6, etc.)in mice with postinfluenza S. aureus infection." (PMID 40134435, 2025). "The overlapping roles of cytokines, particularly IL-3, IL-6, IL-10, IL-17, TNF-α, and TGF-β, suggest significant crosstalk between pathways in radiation-induced lung injury (RILI) and immunotherapy-related lung injury (IRLI)." (PMID 40299683, 2025). "They observed no changes in TNF, IFN-γ, MIP-1α, and MIP-1β levels in healthy volunteers or trauma patients but did note an increase in IL-8 levels as well as small decreases in IL-6, IL-10, MCP-1, and IP-10 in trauma patients only." (PMID 39480839, 2024). "Looking at only the population of trauma patients, the concentrations of several proteins, including YKL-40 (CHI3L1), IL-6, IL-8, IFNγ, and others, were positively correlated with patient age." (PMID 38903094, 2024). "Liu and collaborators showed that 4-HPA was able to reduce the levels of the pro-inflammatory cytokines TNF-α, IL-1β, IL-6, and HIF-1α and prevent lung oedema in a rat model of acute lung injury." (PMID 39000542, 2024). "An integrative review of 37 studies identified an elevation of IL-6, IL-1β, IL-8 and TNF-α during the first 3 weeks of life as potential, independent predictors of brain injury and neurodevelopmental impairment." (PMID 37049507, 2023).
injury (continued). "Soluble factors from L. reuteri significantly reduced the production of proinflammatory cytokines (i.e., IL-6 and TNF-α) by lipopolysaccharide-stimulated macrophages and alleviated lipopolysaccharide-induced acute lung injury in mice." (PMID 37517995, 2023). "A recent study in China shows that GL reduces the expression level of HIF-1α, inhibits the release of inflammatory cytokines IL-6 and TNF-α, and plays protective roles in acute lung injury." (PMID 35967372, 2022). "In our study, the concentrations of these pro-inflammatory biomarkers (TNF-α, IL-6, IL-1β, and NF-κB) were markedly elevated in lung tissue homogenate of the BLM mice model of acute lung injury." (PMID 35808662, 2022). "In this study, the levels of the pro-inflammatory markers (IL-6, IL-1β, TNF-α, and NF-kB) were high in the pulmonary tissues of the BLM-induced model of acute lung injury." (PMID 36500388, 2022). "It has been shown that inflammatory chemokines, particularly interleukin-6 (IL-6) and tumor necrosis factor-α (TNF-α), play an important role in the onset of acute lung injury." (PMID 36532788, 2022). "The plasma IL6 levels were increased in patients with SCI and head trauma compared with those in healthy controls." (PMID 35453528, 2022). "The neuroinflammatory response, including the production of pro-inflammatory cytokines IL-6 and TNF-α, is also curbed by ketamine treatment following an insult in a traumatic brain injury model." (PMID 33672922, 2021). "It has been proved that the level of IL‐6 in serum and the secretion of cytokines, including IL‐1 β and TNF‐α, increase with the increase of cerebrospinal fluid after brain injury." (PMID 32533644, 2020). "Our results showed that CD significantly reduced synthesis of TNF-α, IL-1β, and IL-6 in serum, indicating that CD treatment alleviated the inflammatory responses due to APAP-induced liver injury." (PMID 33364966, 2020). "WPPs can alleviate liver injury by regulating the serum levels of IL-6, IL-12, TNF-α, and IFN-γ in mice with liver injury, and the effect is similar to that of silymarin." (PMID 31683564, 2019). "However, excessive and prolonged training with insufficient recovery might cause musculoskeletal trauma with increased production of proinflammatory cytokines such as TNF- α, IL-1β, and IL-6, which contributes to symptoms related to performance decrement and exercise-induced fatigue." (PMID 32082125, 2019). "For example, AM suppresses the in vitro secretion and gene transcription of TNF-α and IL-6 in the murine monocyte/macrophage cell line RAW 264.7 and also attenuates TNF-α and IL-1β production in an in vivo acute lung injury mouse model." (PMID 28299347, 2017). "Our previous study found that salidroside attenuated serum IL-6 and TNF-α levels in LPS-induced acute lung injury." (PMID 29333216, 2017). "Asiaticoside reduced the content of IL-6 and TNF-alpha in a dose-dependent manner in acute lung injury." (PMID 24667059, 2014). "NOX1 has been reported to worsen hyperoxia-induced acute lung injury in mice, and NOX4 has been suggested to stimulate microglial IL-6 expression and to hamper neurodegeneration after poststroke ischemia reperfusion injury." (PMID 22529530, 2012). "The negative correlation between GCR-α expression and IL-6 levels with no change in GILZ expression 48 h after head trauma reflects possible GC resistance and thus excess inflammatory response." (PMID 41226738, 2025). "With BMDMs’ activation model and LPS-induced acute lung injury mouse model, we firstly demonstrated that ICD ameliorates IL-6 expression and suppresses p65 and JNK phosphorylation in LPS-stimulated macrophages, and protects mice from acute lung injury induced by LPS." (PMID 36902060, 2023). "On the other hand, another study reported that epigallocatechin gallate (EGCG) could attenuate lipopolysaccharide-stimulated acute lung injury in mice and restrained the liberation of inflammatory cytokines TNF-α, IL-1β, and IL-6." (PMID 36290242, 2022).
injury (continued). "The present study found that the IL-6 expression in PrL was significantly increased on weeks 5 after SNI, and the knockdown of IL-6R in pyramidal neuron of PrL relieved the depression-like behavior induced by nerve injury." (PMID 35690777, 2022). "Likewise, L. plantarum C88 downregulated the expression of NFκB in a LPS/GalN-induced acute liver injury mouse model, which decreased the levels of TNF-α, IL-6, and IL-12 in liver." (PMID 35903291, 2022). "Aerobic exercise can also modulate the inflammatory/anti-inflammatory and oxidative/antioxidative balance in the early stage of LPS-induced lung injury, which leads to a decrease in the release of inflammatory mediators such as TNF-α, IL-6, IL-10, IL-1β, IL-17, GM-CSF, and CXCL1/KC." (PMID 36456896, 2022). "Therefore, excessive pro-inflammatory cytokines, such as IL-1β, IL-6, and TNFα, are considered to be the precursors of APAP-induced liver injury, and these pro-inflammatory cytokines are considered to affect the process of APAP-induced liver injury." (PMID 34639126, 2021). "The earlier studies showed M1 inflammatory mediators like iNOS, Il-1β, IL-6 etc. are the key players to initiate inflammatory processes and ALI and modulation of the M1 inflammatory marker were beneficial for the resolution of acute lung injury." (PMID 32575718, 2020). "Furthermore, NAP effectively suppressed TNF and IL-6 secretion in murine macrophages in vitro and of TNF in head trauma in vivo." (PMID 32466564, 2020). "However, the levels of hepatic TNF-α, IL-1β, IL-4, IL-6, and TGF-β1 were significantly lower in rats with 2-AAF/PH-induced liver injury treated with Pue and RAPA than in untreated rats with liver injury, and IL-10 expression was higher." (PMID 30405406, 2018). "In sharp contrast to the steep increase in hepatic expression of IL-1β, IL-6, TNF-α and MMP-13 in the context of fulminant liver injury induced by D-GalN/LPS, the fibrotic mice were highly resistant to this attack, showing significantly less induction of inflammatory cytokines and MMP." (PMID 28874845, 2017). "The present results exhibited that LPS induced inflammation and immune suppression in the lung via influencing IgM, IgG, IL-1β, IL-6, and TNF-α, while indirubin markedly reduced IgM abundances and IL-1β and TNF-α mRNA abundances in LPS-induced acute lung injury." (PMID 28525368, 2017). "When patients with primary MHTN related kidney injury have decreased CD4+CD25+ cells, their lymphocytes would react significantly more strongly to antigens, leading to higher levels of cytokine (IL-2, IL-4, and IL-6) production." (PMID 27278520, 2016). "In the present study we observed similar to others an upregulation of IL-6 after nerve injury; however it was not affected by PTL." (PMID 26090236, 2015). "In this study MK-886 significantly reduced the elevation of IL-6 and TNF-α level in the shocked rats as compared with induced untreated group suggesting that MK-886 has protective effect in hemorrhagic shock-induced acute lung injury." (PMID 21649921, 2011). "In patients with head injury, moderate hypothermia (32 to 33°C) suppressed increased arterial IL-6 levels, whereas normothermia (36 to 37°C) did not decrease elevated arterial IL-6 levels after brain injury." (PMID 18652703, 2008). "For example, treatment with synaptamide in traumatic brain injury or sciatic nerve chronic constriction injury decreased astrogliosis and immunoreactivity and reduced the levels of inflammatory biomarkers such as glial fibrillary acidic protein (GFAP), S100β, and IL-6." (PMID 38338779, 2024). "Intraperitoneal injection of galangin can remarkably inhibit the LPS-induced synthesis of IL-6 and TNF-α, the change in lung tissue dry/wet weight ratio, and the disruption of lung tissue structure, improving the survival rate of rats with inflammatory lung injury." (PMID 36072628, 2022).